ESR2 (estrogen receptor 2)
Diseases named in the same sentence as ESR2 in open-access papers (continued):
Sharing a sentence is not in itself a finding about the gene and the disease.
tumor (continued). "Furthermore, eight target genes (COL4A3, FAM30A, FCRL5, MDM4, SYNE2, TNFRSF13C, TPTEP2, VAMP1) were systematically positively correlated with ESR2 expression patterns in tumor types with low ESR2 expression as a prognostic factor concerning OS or DFS." (PMID 39201394, 2024). "In our study, both chemerin and CMKLR1 levels in tumor tissues positively correlated with estrogen receptor β (ERβ), which could be confirmed on the mRNA level for CMKLR1 and ESR2 by in silico analysis." (PMID 36900088, 2023). "It is suggested that ISL has the potential to be a novel therapeutic agent for CRC, and ESR2 may be the anti-tumour target of ISL and other phytoestrogens." (PMID 38256877, 2023). "Median age and median tumor size differed between the ESR2-high vs -low subgroup s (p < 0.05)." (PMID 35304506, 2022). "Interactive bodymap indicates that ESR2 is aberrantly expressed in several tumor tissues." (PMID 35719919, 2022). "ESR2 may function in PC as a tumor suppression gene; it preferentially binds phytoestrogens and is likely to protect the prostate epithelium from malignant transformation." (PMID 36230681, 2022). "However, under pathological conditions, ESR1, ESR2, and PGR have been demonstrated to be associated with tumorigenesis and tumor progression." (PMID 34322374, 2021). "Early studies showed that ESR2 exhibited anti-tumor properties." (PMID 32678032, 2020). "The pathway enrichment analysis result showed that ESR1 and ESR2 correlated genes enriched in some immune response and immune cell activity pathways indicated an essential relationship between estrogen receptor and tumor immunity in many cancer types." (PMID 32536040, 2020). "As the Wnt pathway is known to promote proliferation of tumor cells, its up-regulation might be one reason for the increased growth of this cell line transfected with ESR2 siRNA." (PMID 31357971, 2019). "Previous reports have proposed that ESR1 and ESR2 could have a tumor suppressor role in prostate gland." (PMID 29731970, 2018). "Furthermore, ESR2 (ERβ) mRNA expression in T3 tumours was comparable to that of T1 tumours (p = 0.085)." (PMID 29390981, 2018). "To address the clinical relevance of our in vitro findings, we assessed ESR2 expression by IHC staining on tissue microarrays containing tumor specimens of OPSCC patients, which were treated with either definitive or post-surgical radiotherapy with or without adjuvant chemotherapy." (PMID 28166815, 2017). "In the colonic mucosa, estrogen can selectively activate ESR2-mediated regulation of mismatch repair proteins, and pro-apoptotic signaling, and can modulate the inflammatory tumor microenvironment and various immune surveillance mechanisms, thereby exerting anti-tumor effects." (PMID 41415563, 2025). "Our cross-tumor pattern—ESR2-Altered linked to worse OS in BRCA but better OS in UCEC and OV—is broadly consistent with an expression-focused literature suggesting that ERβ activity tends to be protective, while also emphasizing known context and isoform dependencies." (PMID 41153361, 2025). "Moreover, ESR2 expression correlated with tumor stage in our study in KIRC, LUAD, TGCT, and THCA." (PMID 39201394, 2024). "Furthermore, the overexpression of both TFAP2A and ESR2 in NSCLC cells was associated with the overactivation of MAPK signalling, and the combination of PHTPP and osimertinib had a synergistic effect on suppressing tumour growth." (PMID 39695171, 2024). "Therefore, the ESR2 regulation of SYNE2 expression could be tumor-dependent and requires further functional studies." (PMID 39201394, 2024). "Therefore, we categorized tumor types based on the prognostic role of ESR2 expression." (PMID 39201394, 2024). "Finally, we investigated genes displaying similar expression patterns to ESR2 in tumor tissues, identifying potential co-expressed genes that may synergistically affect OS and DFS outcomes." (PMID 39201394, 2024). "Moreover, we carried out correlations between ESR2 expression and tumor stage and grade." (PMID 39201394, 2024).
tumor (continued). "Notably, our findings highlight seven genes (FAM30A, MDM4, POU2AF1, SYNE2, TNFRSF13C, TPTEP2, VAMP1) presenting positive correlations with ESR2 expression patterns in all tumor types with high ESR2 expression as a positive prognostic factor with regard to OS or DFS." (PMID 39201394, 2024). "However, the role of ESR1 or ESR2 had a considerable difference in diverse tumor types." (PMID 32536040, 2020). "Thus, using the TCGA database, we analyze ESR1 and ESR2 mRNA expression in tumor tissues." (PMID 32536040, 2020). "In summary, these data suggested that SMR3A expression serves as a potential surrogate marker for active ESR2 signaling in a subpopulation of radioresistant tumor cells, raising the question, whether pharmacological interference sensitizes these cells to fractionated IR." (PMID 28166815, 2017). "In obese EA patients, enriched pathways were dominated by extra-nuclear estrogen signaling (e.g., ESR1, ESR2, HEY2, MCL1), suggesting a strong hormonal component in TNBC tumor biology." (PMID 41009685, 2025). "In contrast, patients with high MET/ESR2 coexpression had unfavorable tumor features and advanced prognosticators compared to patients with low MET/ESR2 coexpression (p < 0.001)." (PMID 39742369, 2024). "Finally, we investigated genes displaying similar expression patterns as ESR2 in tumor tissues, identifying potential co-expressed genes that may exert a synergistic effect on clinical outcomes, with significant results, including the expression of ACIN1, SYNE2, TNFRSF13C, and MDM4." (PMID 39201394, 2024). "The correlation between the DNA methylation beta-value and the RNA level of ESR1, ESR2, and GPER1 was analyzed through cBioPortal in 19 tumor types." (PMID 38666956, 2024). "The most inspiring phenomena are the higher expression of ESR2 in the male testis than in the female ovary and endometrium and the consistent reduction of GPER1 RNA in different tumor samples when compared with normal tissues." (PMID 38666956, 2024). "Immunohistochemical analysis revealed that the protein expressions of PI3KCG, AKT and P-GSK3β in tumour tissues of ISL-treated mice were down-regulated, while the expression of ESR2 was significantly elevated (p < 0.05)." (PMID 38256877, 2023). "In conclusion, the results clarify the mechanisms by which estrogens, via ESR2, impair MCL tumor progression and provide a possible explanation for the sex-dependent difference in incidence." (PMID 35804870, 2022). "Together, ESR1, ESR2, and PGR are likely closely correlated and have a role in multiple tumor genesis." (PMID 34322374, 2021). "To examine the clinical relevance of ESR1, ESR2, and PGR in pan-cancer, we analyzed the correlations of their expression with tumor stage." (PMID 34322374, 2021). "Genetic alterations and immunological effects of ESR1, ESR2, and PGR were analyzed using the cBioPortal and Tumor and Immune System Interaction Database (TISIDB), respectively." (PMID 34322374, 2021). "The significant different DNA methylation between tumor and healthy tissues was shown in 10 tumor types for ESR1 and eight tumor types for ESR2." (PMID 32536040, 2020). "The number of ERs significantly correlated genes varies considerably in different tumor types (from 0 to 3679 for ESR1 and from 0 to 3667 for ESR2)." (PMID 32536040, 2020). "However, when we further adjust the tumor stage/grade/status of the patients, only LIHC and MESO showed significant survival association with ESR1 mRNA expression, while BRCA, KICH, KIRP, LGG, and PAAD patients survival significant association with ESR2 mRNA expression." (PMID 32536040, 2020). "Fractionated irradiation (IR) revealed an accumulation of tumor cells with prominent SMR3A expression, which was accompanied by an up-regulation of the estrogen receptor 2 (ESR2)." (PMID 28166815, 2017). "So far, experimental data support a model in which ESR2 and SMR3A co-expression after fractionated IR is a characteristic feature for a subpopulation of treatment resistant tumor cells." (PMID 28166815, 2017).
tumor (continued). "This suggests that its targets, such as SH3BP5, NBEA, ZBTB20, ESR2, and ESR1, may escape miR-204-mediated repression, potentially leading to their overexpression, which could promote tumor growth and metastasis." (PMID 41009685, 2025). "Subsequently, we assessed the combined influence of those genes and ESR2 on clinical outcomes in patients with TCGA tumor types as they did not present any impact on OS or DFS on their own." (PMID 39201394, 2024). "Given the synergistic effect of ESR2 in targeted therapy of NSCLC, the present study demonstrated that the combination of the ESR2 inhibitor TPHPP and osimertinib had a greater influence on tumour progression via in vivo and in vitro assays." (PMID 39695171, 2024). "Unlike ESR1, estrogen receptor 2 (ESR2) is expressed in CRC and is associated with tumor suppression." (PMID 39327445, 2024). "In summary, the present study revealed that TFAP2A promotes NSCLC progression by mediating ESR2 and subsequently activating MAPK signalling pathways, and combined treatment with the ESR2 inhibitor TPHPP and targeted therapy synergistically inhibits tumour growth and improved patient prognosis." (PMID 39695171, 2024). "Significant associations were observed between tumor survival and ESR1 methylation (159 records, 68 negative and 91 positive), ESR2 methylation (46 records, 27 negative and 19 positive), and GPER1 methylation (67 records, 35 negative and 32 positive)." (PMID 38666956, 2024). "Conversely, one target gene, RAC1, showed a negative correlation with ESR2 expression patterns in those tumor types." (PMID 39201394, 2024). "Furthermore, in selected tumor types, we extended our analysis to investigate overall survival (OS) and disease-free survival (DFS) in the context of ESR2 expression." (PMID 39201394, 2024). "Statistical analysis using two-way ANOVA showed that tumor grade does not affect ESR2 mRNA or protein levels, while menopausal status affects mRNA expression (p = 0.037) but not protein levels." (PMID 36769338, 2023). "Moreover, the mRNA expression levels of ESR2 and GPER1 were also significantly lower in PTC tumor specimens than in adjacent normal tissues in female patients." (PMID 35162942, 2022). "The ESR2-mediated responses, as studied in Granta-519 MCL tumors, involve the alteration of several signaling pathways in the tumor cells as well in the TME that help to clarify the mechanism for the impaired tumor progression seen by estrogens." (PMID 35804870, 2022). "From the ginsenoside-target-pathway network, we observed that EGFR, ESR1, ESR2, HSP90AA1, and RELA are all critical genes that we should focus on, which may reveal the anti-tumor mechanism of G-Rk1 and G-Rg5." (PMID 34199025, 2021). "The results of the present study revealed that the expression of ESR1 and PGR correlated with the tumor stage, whereas the expression of ESR2 did not." (PMID 34322374, 2021). "Our studies investigate the importance of Esr1 and Esr2 in HCC development in female mice, and show that Esr1, but not Esr2, is a key mediator of tumor outcome." (PMID 34068249, 2021). "Relative E2 amount was positively associated with ESR2 (ERβ) mRNA expression (r = 0.61; P = .0358), but not ESR1 (ERα) mRNA expression in women with ER+/PR+ tumor." (PMID 31853538, 2020). "We found that relative E2 amount was associated with ESR2 (ERβ) mRNA, but not that of ESR1 (ERα) in women with ER+/PR+ tumor." (PMID 31853538, 2020). "These analyses also showed an enrichment for hypomethylated binding sites of transcription factors (e.g., ESR1, ESR2, FOXA2) and histone proteins (e.g., H3K4m1, H3K4m2, H3K4m3, H3K27m3, H3K9m3) in GBM2 compared to GBM1, suggesting a role for these factors in tumor progression." (PMID 32779022, 2020). "Another interesting finding was high expression of estrogen receptor 2 (ESR2) in the recurrent, but not the primary tumour." (PMID 31747973, 2019).
tumor (continued). "Importantly, ESR2 expression was inversely correlated with CRC progression and dKO of Esr1 or Esr2 in ovariectomized ApcMin/+ resulted in increased rate of tumor formation." (PMID 29383180, 2017). "In the current study, we demonstrate prominent SMR3A expression in tumor cells upon fractionated irradiation (IR) and provide experimental evidence that induced SMR3A expression serves as a surrogate maker for active estrogen receptor 2 (ESR2) signaling in radioresistant tumor cells." (PMID 28166815, 2017). "Nevertheless, a negative staining in a tumor biopsy taken at the time point of diagnosis or during primary surgery does not exclude induction and/or expansion of ESR2-positive tumor cells during fractionated radiotherapy." (PMID 28166815, 2017). "In case of ESR2, tumor-adjacent (p < 0.001) and tumor-distant tissues (p < 0.001) but not the tumors showed significantly higher methylation levels than normal breast tissues from healthy women." (PMID 28403857, 2017). "The results of the network prediction indicate that ESR2, PIK3CG and GSK3β might be the key targets of ISL against CRC, which was verified by molecular docking, and that its anti-tumour mechanisms might be related to the oestrogen and PI3K/AKT signalling pathway." (PMID 38256877, 2023). "For the following genes, a correlation was found between the methylation levels in tumors and those in tumor-adjacent tissues: CDKN2A (promoter) (r = 0.927, p < 0.001); BRCA1 (r = 0.878, p < 0.001); APC (r = 0.706, p = 0.001), ESR1 (r = 0.545, p = 0.019) and ESR2 (r = 0.543, p = 0.024)." (PMID 28403857, 2017). "Nevertheless, ESR1 and ESR2 expression on human GBM-derived cell lines were lower compared to healthy astrocytes, reinforcing the hypothesis of the studies above, which establish that the expression of both ER subtypes is inversely proportional to the tumor evolution degree." (PMID 32825553, 2020). "There was no obvious relationship between the survival rate of the tumor patients and the RNA levels of ESR1 and ESR2 (p > 0.05)." (PMID 37762356, 2023). "The dMMR tumor in ≥70Rt is an attractive candidate to explain this hypothesis because it has the background of NonCa with the ESR2-CA SS genotype, high ER-β expression, and a high estrogen concentration." (PMID 36901930, 2023). "However, we detected a positive staining for ESR2 expression as a common event in OPSCC, while ESR1-positive tumor cells were a rather rare event (data not shown)." (PMID 28166815, 2017). "However, in line with our data two studies found a frequent expression of ESR2 but not ESR1 in HNSCC cell lines and tumor tissues, suggesting a more prominent role of ESR2-related signaling." (PMID 28166815, 2017). "The luminal B tumours exhibit the highest ESR1 and lowest ESR2 expression among all subtypes, with ESR2 being particularly scarce—a feature that distinguishes luminal B from ERα-negative cancers, where ESR2 may have clinical relevance." (PMID 41007296, 2025).
cancer (469 papers, 2002 to 2026). A tumor composed of atypical neoplastic, often pleomorphic cells that invade other tissues. "The context-dependent nature of ESR2 variants has been corroborated through their various associations with different cancers." (PMID 41153361, 2025). "Many of these phenotypes from the top network are directly related to the activity of ESR2 and AR, such as reproductive system-associated cancers." (PMID 39598420, 2024). "Variants of the estrogen receptor b (ESR2) gene have been associated with different types of cancer." (PMID 35573183, 2022). "In the stratified analysis by cancer type, 10 studies were used to evaluate the relationship between ESR2 rs4986938 polymorphism and BC risk." (PMID 31523634, 2019). "The association between estrogen receptor-β (ESR2) rs4986938 polymorphism and the risk of various types of cancer have been investigated in previous studies." (PMID 31523634, 2019). "In the present meta-analysis, we systematically analyzed the association between ESR2 rs4986938 and cancer risk." (PMID 31523634, 2019). "Here, we conducted a meta-analysis to investigate the association between ESR2 rs4986938 polymorphism and the risk of cancer." (PMID 31523634, 2019). "As one of the most common form of genetic variation in ESR2, rs4986938 polymorphism has been investigated in numerous studies to evaluate the association with cancer risk in multiple cancers." (PMID 31523634, 2019). "More recently, several new studies have also reported an association between ESR2 rs4986938 and cancer risk." (PMID 31523634, 2019). "Epidemiological studies have revealed several functional polymorphisms of estrogen receptor beta (ESR2) for cancer risk, but relevant study in CRC is limited, particularly in men." (PMID 22759347, 2012). "ESR2 forms 3 sub-clusters which separate the normal tissue form from the cancer associated form and all 3 sub-clusters show differences in the degree of predicted intrinsic disorder." (PMID 21143794, 2010). "A marginally significant increase in the risk of developing cancer was observed among women carrying at least one ESR2 *38A allele compared to the women homozygous for the GG genotype (all participants: OR 1.40; 95% CI 0.88, 2.25)." (PMID 16808847, 2006). "The oncogenic potential of ESR2 gene variants was assessed using the CScape and CScape-somatic prediction tools, which assign oncogenicity scores from 0 to 1 and classify mutations as either drivers or passengers based on their role in cancer development." (PMID 41153361, 2025). "Overall, these findings indicate that mutations associated with cancer could influence the ESR2 interactome network, potentially leading to uncontrolled transcription and tumorigenesis." (PMID 41153361, 2025). "Thus, patients’ cancers exhibited high expression levels of PTGS2/ESR2/EGFR/JUN/MMP2 genes’ signatures are associated with poor prognosis." (PMID 39707884, 2024). "A truncated splice variant isoform (ERβ5) encoded by ESR2 is highly expressed in cancers." (PMID 31778358, 2020). "Likewise, women currently using HT who were homozygous GG for ESR2 rs1271572 had an increased risk of death due to cancer, while those with a T allele had a reduced risk of all-cause death." (PMID 22457817, 2012). "The study aimed to develop an integrative, multi-tool silico framework that prioritizes ESR2 variant classes, annotates their biological context, and evaluates their potential clinical relevance through pathway/regulatory analyses, as well as pan-cancer survival modeling." (PMID 41153361, 2025). "Moreover, splice variants of the ESR2 gene (ERβ1, ERβ2, etc.)activate cancer cells in various ways." (PMID 37345182, 2023). "ESR2+ stromal cells from control eutopic tissue were positively enriched for multiple pathway types including cell signaling pathways, metabolism, and cancer-related pathways." (PMID 41000819, 2025).